NECTIN4 (nectin cell adhesion molecule 4)
Diseases named in the same sentence as NECTIN4 in open-access papers (continued):
Sharing a sentence is not in itself a finding about the gene and the disease.
lung carcinoma (23 papers, 2011 to 2026). "CD112 and nectin-4 appeared to be diagnostic in lung cancer; CD112 was reportedly a stronger diagnostic indicator, but neither biomarker was prognostic or predictive." (PMID 34507594, 2021). "Nectin4 is a recently discovered tumor associated antigen expressed in cancers that constitute relevant unmet clinical needs, including the undruggable triple negative breast cancer, pancreatic ductal carcinoma, bladder/urothelial cancer, cervical cancer, lung carcinoma and melanoma." (PMID 37251078, 2023). "In addition, a soluble form of Nectin-4/PVRL4 is present in the sera of breast and lung cancer patients, which could have diagnostic applications for the screening of these cancers." (PMID 31043633, 2019). "TCGA Pan-Cancer analysis demonstrated that NECTIN4 amplifications occur frequently in other cancers, for example, in 5%-10% of breast and lung cancers." (PMID 38657187, 2024). "We first evaluated the expression level of nectin-4 in three canine lung cancer cell lines, AZACL1, AZACL2 and CLAC, using flow cytometry." (PMID 37875555, 2023). "Nectin-4 is expressed on three canine lung cancer cell lines (CLAC, AZACL1, AZACL2) and rMV-SLAMblind was able to infect these cell lines." (PMID 37875555, 2023). "In the case of human lung cancer cell lines, 6 out of 8 nectin-4 positive cell lines were killed by rMV-SLAMblind treatment." (PMID 37875555, 2023). "Because the number of cell lines tested in this study was small due to availability of canine lung cancer cell lines, we found only one third of the nectin-4 positive canine cancer cells was killed by rMV-SLAMblind treatment." (PMID 37875555, 2023). "On the other hand, high nectin‐4 expression has been found in more than 50% of human breast, pancreatic, and lung cancer patients." (PMID 35905293, 2022). "A recent study demonstrated that an antibody-drug conjugate targeting Nectin-4 inhibited tumor growth in xenografts models of breast, bladder, pancreatic and lung cancer." (PMID 28038455, 2017). "A similar proliferative advantage for Nectin-4 expressing cells was recently shown in pancreatic cancer and in lung cancer." (PMID 28038455, 2017). "Our findings suggest that rMV-SLAMblind that targets Nectin-4 is effective for lung cancer treatment." (PMID 26317644, 2015). "Flow cytometry was used to evaluate Nectin-4 expression in a panel of lung cancer cell lines, including 14 NSCLC lines and eight SCLC lines." (PMID 26317644, 2015). "In this study, we demonstrated that rMV-SLAMblind can infect and kill lung cancer cells, by targeting Nectin-4, in particular NSCLC cells, both in vitro and in vivo resulting in cell death and tumor regression." (PMID 26317644, 2015). "Recently, it has been reported that Nectin-4 is selectively up-regulated in a variety of tumor cell types including breast, ovarian, and lung cancer cells." (PMID 26317644, 2015). "Nectin-4 (Poliovirus Receptor-Related Protein 4) is another emerging molecular target in ADC design, implicated in the onset and development of various epithelial cancers, including breast, urothelial, and lung carcinomas." (PMID 39770542, 2024). "However, it is worth noting that Nectin-2 seems to have an advantage over Nectin-4 in diagnosis of lung cancer." (PMID 38606099, 2024). "Similarly, Takano reported that nearly two-thirds of patients presented with up-regulation of Nectin-4 and had a very poor survival in lung cancer." (PMID 35953862, 2022). "As a tumour marker, elevated serum nectin‐4 has been reported to be useful in human lung cancer." (PMID 35905293, 2022). "Lung cancer cells, particularly those of non-small-cell lung cancer, are known to express Nectin-4." (PMID 26317644, 2015). "In a mouse model, lung cancer cells that express Nectin-4 injected into the flanks of mice showed increased tumor proliferation compared to lung cancer cells without endogenous Nectin-4 expression." (PMID 28038455, 2017).
lung carcinoma (continued). "Thus, the serum concentration of CD112 was more effective in identifying individuals with and without lung cancer than serum nectin-4 (alone or in combination with CD112)." (PMID 34507594, 2021). "In their studies, treatment with their mAb against Nectin-4 did not reduce tumor size in lung cancer xenografts; indicating that blocking Nectin-4 cell adhesion may be an important component of therapeutic efficacy for a mAb in this setting." (PMID 28038455, 2017).
pancreatic cancer (23 papers, 2015 to 2025). "In human pancreatic cancer, the expression of nectin‐4 has also been reported to be associated with prognosis." (PMID 35905293, 2022). "Nectin-4 is a cell adhesion molecule that is overexpressed in pancreatic cancer and has been associated with poor prognosis." (PMID 33546207, 2021). "Association of Nectin-4 expression with markers of tumor proliferation was analyzed in pancreatic cancer patients." (PMID 31572728, 2019). "Nectin-4 overexpression has been reported in ductal breast carcinoma, lung adenocarcinoma, and pancreatic cancer; and high Nectin-4 expression in those tumors was associated with disease progression or poor prognosis." (PMID 28038455, 2017). "Further studies will be warranted to determine the association between Nectin-4 expression and virus infection in actual pancreatic cancer." (PMID 25888293, 2015). "In addition, based on the previous studies on Nectin-4, we aimed to better understand the underlying functions of Nectin-4 in pancreatic cancer." (PMID 25888293, 2015). "Furthermore, we investigated the association of Nectin-4 in pancreatic cancer with tumor proliferation, angiogenesis and immunity by using immunohistochemistry and siRNA interference method." (PMID 25888293, 2015). "Furthermore, these findings suggest that the downregulation of nectin-4 is associated with the loss of cell-to-cell adhesion in pancreatic carcinoma." (PMID 25690753, 2015). "Therefore, we hypothesized that Nectin-4 might be associated with angiogenesis in pancreatic cancer." (PMID 25888293, 2015). "Given this increased expression, anti-NECTIN4 ADCs were trialed in bladder, breast, lung and pancreatic cancers and have demonstrated responses in preclinical xenograft models." (PMID 41164107, 2025). "Nectin‐4 has been reported to be expressed in human lung, ovarian, and pancreatic cancers and promotes tumour growth." (PMID 35905293, 2022). "Nectin-4 has been identified as a prognostic marker in different cancers such as esophageal, lung, breast and pancreatic cancer." (PMID 36136143, 2022). "In pancreatic cancer, Nectin-4 expression is correlated with poor outcome, and in UTUC, high expression of Nectin-4 is associated with poor prognosis in high-risk patients." (PMID 36139571, 2022). "They found a positive correlation between Nectin-4 and Ki67 proliferation index and siRNA knockdown of Nectin-4 inhibited proliferation of pancreatic cancer cells in vitro." (PMID 36136143, 2022). "Patients with NECTIN4-high tumors had significantly poorer overall survival than those with low ones in pancreatic cancer." (PMID 33478111, 2021). "NECTIN4 is abnormally highly expressed and contributes to tumor proliferation in pancreatic cancer and hepatocellular carcinoma." (PMID 34925438, 2021). "This study includes BT8009-100 as a monotherapy or in combination with nivolumab (an anti-PD-1 antibody) in patients with nectin-4-expressing advanced solid tumours, including pancreatic cancer." (PMID 33546207, 2021). "Nectin-4 is highly expressed in urothelial, breast, lung, and pancreatic carcinomas, and EV binds to cells that express Nectin-4 with high affinity, initiating the internalization and release of MMAE in the target cells." (PMID 32751328, 2020). "In human pancreatic carcinoma, the over-expression of Nectin-4 significantly promotes the proliferation of cancer cells and contributes to the intra-tumoral angiogenesis, and it can also be used as an important prognostic predictor for the patients." (PMID 31043861, 2019). "In pancreatic cancer, Nectin-4 expression detected by immunohistochemistry correlated with vascular endothelial growth factor expression by quantitative RT-PCR." (PMID 28038455, 2017). "In this study, we tried to clarify the clinical importance of Nectin-4 expression in human pancreatic cancer." (PMID 25888293, 2015). "Nectin-4 expression was investigated in 123 patients with pancreatic cancer by immunohistochemistry." (PMID 25888293, 2015).
pancreatic cancer (continued). "We then investigated the potential roles of Nectin-4 in pancreatic cancer, and found several important findings." (PMID 25888293, 2015). "When transfected with Nectin-4 siRNA in human pancreatic cancer cell lines, Capan-2 and BxPC-3, for up to 72 hours, both mRNA and protein expressions of Nectin-4 were substantially reduced." (PMID 25888293, 2015). "Next, to further investigate the functions of Nectin-4 in pancreatic cancer, we evaluated the involvement of Nectin-4 in pancreatic cancer cell proliferation." (PMID 25888293, 2015). "Overall, the mean percentage of Nectin-4 positive cells in pancreatic cancer tissues was 51.4% (standard deviation 23.5%)." (PMID 25888293, 2015). "We first evaluated the Nectin-4 expression in 123 actual human pancreatic cancer tissues by immunohistochemistry." (PMID 25888293, 2015). "Further studies will be needed to elucidate the mechanism(s) by which pancreatic carcinomas downregulate nectin-4 expression, which can lead to the invasion and spread of such carcinomas." (PMID 25690753, 2015). "However, numerous studies revealed that Nectin-4 is specifically up-regulated in various cancers, including breast, lung, ovarian, gastric, and pancreatic cancer, and its expression is closely related to tumor oncogenesis and worse prognosis of the patients." (PMID 35953862, 2022). "In addition, NECTIN4 expression was reported to be positively correlated with Ki67 and the silencing of NECTIN4 inhibited the proliferation of human pancreatic cancer cells, implying its role in the proliferation of tumor cells." (PMID 33478111, 2021). "This suggests that nectin-4 may play a role in pancreatic cancer cell proliferation and angiogenesis, respectively." (PMID 33546207, 2021). "Furthermore, we directly examined the function of Nectin-4 in pancreatic cancer cell using siRNA silencing." (PMID 25888293, 2015). "Taken together, these data suggested that Nectin-4 expression might play an important role in pancreatic cancer." (PMID 25888293, 2015). "This study focused on the clinical significance of Nectin-4 expression in pancreatic cancer." (PMID 25888293, 2015). "Furthermore, it was also supported by the data showing that the siRNA knockdown of Nectin-4 significantly inhibits the proliferation of human pancreatic cancer cells." (PMID 25888293, 2015). "In addition, siRNA-mediated gene silencing of Nectin-4 significantly inhibited the cell proliferation in human pancreatic cancer cells, Capan-2 and BxPC-3." (PMID 25888293, 2015). "We have shown for the first time that Nectin-4 is overexpressed in human pancreatic cancer." (PMID 25888293, 2015). "Importantly, multivariate analysis indicated that Nectin-4 expression had a significant independent prognostic value in pancreatic cancer (HR = 1.721, 1.085-2.730; P = 0.021)." (PMID 25888293, 2015). "We first examined Nectin-4 expression in actual pancreatic cancer tissue by immunohistochemistry." (PMID 25888293, 2015). "Nectin-4 may be novel therapeutic target for pancreatic cancer." (PMID 25888293, 2015). "Nectin-4 is a significant prognostic predictor, and may play a critical role in pancreatic cancer." (PMID 25888293, 2015). "First, Nectin-4 might be involved in the proliferation of pancreatic cancer cells." (PMID 25888293, 2015). "Finally, we investigated the immunomodulatory function of Nectin-4 in human pancreatic cancer." (PMID 25888293, 2015). "Another ongoing clinical trial (NCT03932565) evaluates intratumoral injection of Nectin4/FAP-targeted fourth-generation CAR-T cells (expressing IL-7 and CCL19, or IL12) for the treatment of Nectin4-positive advanced malignant solid tumors (NSCLC, breast, ovarian, bladder or pancreatic cancer)." (PMID 35211124, 2022). "Although the precise underlying mechanism is still not revealed, our data suggested that Nectin-4 might be critically involved in tumor angiogenesis in pancreatic cancer." (PMID 25888293, 2015).
pancreatic cancer (continued). "Nectin-4/PVRL4 has also been proposed as a therapeutic target of primary and metastatic triple-negative breast cancers, as well as of lung, bladder, and pancreatic cancers which could potentially be treated with Nectin-4/PVRL4 antibodies conjugated to anti-neoplastic agents." (PMID 31043633, 2019).
triple-negative breast carcinoma (15 papers, 2019 to 2025). An invasive breast carcinoma which is negative for expression of estrogen receptor (ER), progesterone receptor (PR), and human epidermal growth factor receptor 2 (HER2). "This is in accordance with an immunohistochemical study among patients with triple-negative breast cancer, where a higher Nectin-4 expression was significantly associated with a lower T-stage and absence of lymph node metastases." (PMID 37480387, 2023). "In line with our results, in a cohort of 148 patients with triple negative breast cancer higher staining intensity of Nectin-4 in immunohistochemical analysis was associated with a significantly better survival, lower T stage and lower pN stage." (PMID 36136143, 2022). "In triple-negative breast cancer cells, treatment with N41mab-vcMMAE comprising a human anti-nectin-4 monoclonal antibody conjugated to monomethyl auristatin-E (MMAE) resulted in inhibition of cell proliferation in vitro and reduced metastasis in vivo." (PMID 40507273, 2025). "In tumor specimens of 5673 triple negative breast cancer patients Nectin 4 has been identified as cell surface biomarker." (PMID 31137558, 2019). "In addition, Rabet and colleagues demonstrated that patients who had higher expression of Nectin-4 were more likely to suffer a shorter life compared with those with down-regulation of Nectin-4 in triple-negative breast cancer (TNBC)." (PMID 35953862, 2022). "While a higher protein expression has been shown to be associated with a worse OS in several solid tumors, recent studies among patients with triple-negative breast cancer and HNSCC showed a more favorable OS for tumors with a high Nectin-4 expression." (PMID 37480387, 2023).
measles (14 papers, 2011 to 2025). A highly contagious viral infection caused by the measles virus. "“Nectin-4-blind” viruses largely recapitulated the immuno-pathogenesis of measles in humans, resulting in lymphocyte infection and depletion." (PMID 38415596, 2024). "Several different laboratory and wild-type strains of measles were tested, and all were able to use Nectin-4 as a receptor." (PMID 27657109, 2016). "Some hormone receptors are used by viruses to facilitate cell entry, and although this has not been shown for GH, prolactin, or their receptors, it is notable that the protein nectin-4, which interacts with the prolactin receptor, is used in this way by some viruses, including measles." (PMID 40105703, 2025). "Nectin-4 is also expressed by keratinocytes and endothelial cells, suggesting a potential role for these cell types in the pathogenesis of the characteristic measles skin rash." (PMID 27483301, 2016). "Both CD150 and nectin-4 play crucial roles in the pathogenesis of measles." (PMID 27483301, 2016). "Clearly, the exact role of nectin-4 in measles pathogenesis in the human remains to be elucidated, especially with respect to how the extensive infiltration of MV-infected immune cells and concomitant epithelium disruption impinges on nectin-4 expression levels on adjacent epithelial cells." (PMID 29743202, 2018). "In order to understand the pathogenesis of measles skin rash, it is important to understand both the architecture of the skin and the spatial organization of cell subsets that express either CD150 or nectin-4." (PMID 33031460, 2020). "A case of vaccine-induced measles (case 18) was particularly significant and important because, in theory, the virus could use CD46, CD150, and nectin-4 as cellular receptors." (PMID 29743202, 2018). "Besides CD150+ and nectin-4+ cells, other cells that express DC-SIGN or Langerin could play a role in the pathogenesis of measles skin rash, since DC-SIGN and Langerin facilitate attachment, but not entry, of MV and thus potentially help in spreading the infection in the skin." (PMID 33031460, 2020). "Next, we showed that SSPE MeV-Hs efficiently interact with known wild-type MeV receptors, SLAM and nectin-4, but not with the CD46 receptor used by the live attenuated measles vaccine." (PMID 29466428, 2018).